RNU6-1164P (RNA, U6 small nuclear 1164, pseudogene)
Gene: Small nuclear RNA gene on chromosome 5 (134,701,172 to 134,701,278, reverse strand). Ensembl gene ENSG00000201298.
Homologues: Orthologues: chimpanzee U6 (99% identical), rat U6 (87% identical). Paralogues in human: RNU6-12P (90% identical), RNU6-13P (90% identical), RNU6-31P (90% identical), RNU6-32P (90% identical), RNU6-1 (89% identical), RNU6-11P (89% identical), RNU6-15P (89% identical), RNU6-17P (89% identical), RNU6-18P (89% identical), RNU6-19P (89% identical), RNU6-2 (89% identical), RNU6-37P (89% identical), and 1285 more.